VN1R2 (vomeronasal 1 receptor 2)
Description:
Putative pheromone receptor.
Synonyms: V1RL2
Tractability: Small molecule: it belongs to a druggable protein family. Antibody: UniProt places it where antibodies can reach, with medium confidence; UniProt predicts a signal peptide or a membrane-spanning region; its Gene Ontology location is reachable by antibodies, with medium confidence.
Gene: Protein-coding gene on chromosome 19 (53,258,292 to 53,261,837, forward strand). Ensembl gene ENSG00000196131.
Subcellular location: Cell membrane
Gene Ontology:
Molecular function: pheromone binding; pheromone receptor activity
Biological process: G protein-coupled receptor signaling pathway; sensory perception of chemical stimulus
Cellular component: plasma membrane; membrane
Genetic constraint (gnomAD): Loss-of-function variants: 0 observed, 0.0767 expected, observed/expected ratio (o/e) 0, 90% interval 0 to 1.89. That is too few expected variants to judge how well the gene tolerates losing a copy. Missense variants: 365 observed, 423.58 expected, observed/expected ratio (o/e) 0.86, 90% interval 0.79 to 0.94. Synonymous variants: 138 observed, 158.91 expected, observed/expected ratio (o/e) 0.87, 90% interval 0.75 to 1.
Homologues: Orthologues: rabbit ORYCUNV1R1579 (52% identical), rabbit ORYCUNV1R1637 (51% identical). Paralogues in human: VN1R4 (43% identical), VN1R1 (32% identical), VN1R5 (18% identical).
Diseases named in the same sentence as VN1R2 in open-access papers:
VN1R2 is named in the same sentence as 1 disease in open-access papers, as found by Europe PMC text mining. Sharing a sentence is not in itself a finding about the gene and the disease. The quoted sentences say what the papers report.
ovarian carcinoma (1 paper, 2021). A malignant neoplasm originating from the surface ovarian epithelium. "Our results show that ADIRF, SLC2A5, C3orf86, HSPA1B are among the most significant PCa biomarkers, while MTRNR2L1, EEPD1, TEPP and VN1R2 are jointly important biomarkers across prostate, breast and ovarian cancers." (PMID 34001952, 2021).